YTHDF1 (YTH N6-methyladenosine RNA binding protein F1)
Diseases named in the same sentence as YTHDF1 in open-access papers (continued):
Sharing a sentence is not in itself a finding about the gene and the disease.
breast cancer (continued). "We also found that YTHDF1 was increased in breast cancer samples." (PMID 36077054, 2022). "However, details about how METTL3 regulates YTHDF1-recognized ARHGAP5 to promote breast cancer progression need to be investigated in the future." (PMID 36077054, 2022). "Herein, we demonstrate that the YTHDF1 upregulation is a driving factor in breast cancer cells, which could enhance the proliferation potential and invasiveness of breast cancer cells by promoting protein translation of PKM2 to enhance glycolysis." (PMID 35319018, 2022). "Nevertheless, the role of YTHDF1-medaited m6A modification in the hypoxia-driven emergence, development, and metastasis of breast cancer cells remains largely unknown, which hampers the potential therapeutic exploitation of the associated mechanisms." (PMID 35319018, 2022). "Furthermore, we monitored the effect of YTHDF1 overexpression on the oncogenicity of breast cancer cells in BALB/C mice, which was assessed by monitoring the tumor size changes after injecting YTHDF1 OV transfected 4T1 cells into 4-week-old female BALB/C mice." (PMID 35319018, 2022). "YTHDF1 is not only a tumor promoter but also a target to overcome chemoresistance in breast cancer." (PMID 35279688, 2022). "At the same time, the knockdown of YTHDF1 can significantly inhibit EMT in breast cancer." (PMID 35197112, 2022). "Collectively, our study proposed a novel regulatory pathway of YTHDF1, which provided a new idea for breast cancer treatment and suggested that YTHDF1 may be a potential biomarker and therapeutic target for breast cancer patients." (PMID 35197112, 2022). "We also observed the effects of YTHDF1 on the prognosis of breast cancer patients." (PMID 35197112, 2022). "We then investigated the role of YTHDF1 on the invasion capability of breast cancer cells." (PMID 35197112, 2022). "Furthermore, functional experiments such as the CCK-8 assay, EdU assay, wound healing assay, transwell invasion assay and cell cycle assay were used to determine the biological role of YTHDF1 in breast cancer." (PMID 35197112, 2022). "In addition, flow cytometry analysis showed that re-expressing PKM2 can reverse the apoptosis induced by YTHDF1 knockdown, while the combined treatment of PKM2 knockdown and YTHDF1 overexpression still led to severe apoptosis of breast cancer cells." (PMID 35319018, 2022). "Databases were used to analyze the potential role of YTHDF1 in breast cancer." (PMID 35279688, 2022). "We also analyzed the expression of YTHDF1 in 12 matched pairs of breast cancer and adjacent normal tissues from real-life patients via western blot, of which the results consistently revealed that YTHDF1 was substantially upregulated in breast cancer tissues (Original western blot data 1)." (PMID 35319018, 2022). "We also observed that YTHDF1 was increased in breast cancer samples." (PMID 36077054, 2022). "We further investigated the involvement of YTHDF1-PKM2 axis in breast cancer progression and found that re-expressing PKM2 after YTHDF1 knockout could efficiently restore the glycolysis activity in breast cancer cells (Original western blot data 8)." (PMID 35319018, 2022). "DEGs between high and low YTHDF1 expression in breast cancer." (PMID 34434939, 2021). "YTHDF1 up-regulation was confirmed in breast cancer in the GSE42568 dataset (p = 5e-09)." (PMID 34434939, 2021). "Except for breast cancer, up-regulation of YTHDF1 was found in various cancers, indicating that YTHDF1 could be an oncogene." (PMID 34434939, 2021). "The correlations between YTHDF1 expression and tumor-infiltrating immune cells in breast cancer." (PMID 34434939, 2021).
breast cancer (continued). "Our data were indicative that YTHDF1 might modulate the immune microenvironment of breast cancer, thereby, affecting tumor progression as well as immunotherapy efficacy." (PMID 34434939, 2021). "In addition, we deduced that YTHDF1 may be employed as a biomarker for breast cancer with a bad prognosis." (PMID 38339157, 2024). "We speculate that YTHDF1 may serve as a biomarker for poor prognosis and differential diagnosis, impact the growth of breast cancer cells via the ceRNA network axis, and be a target for immunotherapy against breast cancer." (PMID 38339157, 2024). "Likewise, the m6A reader YTHDF1 enhances glycolysis in breast cancer cells by upregulating PKM2." (PMID 37192910, 2023). "Herein, our work demonstrates that YTHDF1, a m6A-binding protein capable of inducing the translation of the m6A-marked mRNAs, is abnormally upregulated in multiple types of breast cancer cell lines and has major roles in driving the genesis, proliferation and metastasis of breast cancer cells." (PMID 35319018, 2022). "Our work identified that the abnormal YTHDF1 in breast cancer cells was driven by the hypoxic microenvironment, which could induce the expression of HIF1α while inhibiting endogenous miR-16-5p, of which the latter could interact with 3′UTR of YTHDF1 mRNA to inhibit YTHDF1 expression." (PMID 35319018, 2022). "In addition, we determined that PKM2 is a target gene that could activate YTHDF1 to facilitate the occurrence and development of breast cancer." (PMID 35319018, 2022). "Therefore, we silenced YTHDF1 in breast cancer cell lines to investigate whether YTHDF1 has effects on ARHGAP5 mRNA and protein levels." (PMID 36077054, 2022). "In addition to the proliferation analysis, it was found that the YTHDF1 knockdown could also suppress the colony formation of breast cancer cells." (PMID 35319018, 2022). "We also used specific siRNAs to silence YTHDF1 in breast cancer cells and observed that YTHDF1 knockdown would significantly inhibit cell proliferation through inducing apoptosis, indicating that YTHDF1 could be exploited as a potential therapeutic target for breast cancer treatment." (PMID 35319018, 2022). "Also, HNRNPC and YTHDF1 have an effect on prognosis in breast cancer patients." (PMID 34277622, 2021). "It has been shown that higher YTHDF1 and YTHDF3 expressions were correlated with a shorter survival in breast cancer (BC), and the importance of YTHDF3 as an independent risk factor for BC has been a topic of significant research." (PMID 33692959, 2021). "For example, YTHDF1 accelerates FOXM1 translation and drives breast cancer (BC) metastasis through m6a modification." (PMID 39060874, 2024). "The YTHDF1/FOXM1 regulatory pathway contributes to metastasis and growth of breast cancer through regulating PKM2 to affect the glycolysis and progression of breast cancer." (PMID 38339157, 2024). "m6A promotes breast cancer lung metastasis by increasing the stability of the KRT7-AS/KRT7 mRNA duplex and translation of KRT7, where YTHDF1/eEF-1 is involved in FTO-regulated KRT7 mRNA translational extension." (PMID 38339157, 2024). "In breast cancer cell lines (MCF7 and MDA-MB-231), silencing of YTHDF1 increased sensitivity to Adriamycin, cisplatin, and olaparib, highlighting the significance of YTHDF1 in drug resistance and DNA damage repair." (PMID 38328550, 2024). "YTHDF1/eEF1-mediated translational elongation of KRT7 mRNA and YTHDF3-induced mRNAs translation of ST6GALNAC5, GJA1, and EGFR is involved in breast cancer lung and brain metastasis, respectively." (PMID 36999016, 2023). "The downregulation of YTHDF1 suppressed the proliferation and epithelial-mesenchymal transformation (EMT) and induced cell cycle arrest in breast cancer cells." (PMID 36835633, 2023). "Through recognizing and binding to the m6A-modified mRNA of FOXM1, YTHDF1 accelerated the translation process of FOXM1 and promoted breast cancer metastasis." (PMID 35197112, 2022).
breast cancer (continued). "YTHDF1 depletion repressed the proliferation, invasion and epithelial-mesenchymal transformation (EMT) and induced G0/G1 phase cell cycle arrest of breast cancer cells in vitro and in vivo." (PMID 35197112, 2022). "We found that YTHDF1 overexpression led to a significant increase in the size and PKM2 expression level of subcutaneous breast cancer tissues compared with controls (Original western blot data 14)." (PMID 35319018, 2022). "All above results indicate that YHTDF1 is a reader protein of ARHGAP5 m6A in breast cancer cell lines and that METTL3/YTHDF1 controls ARHGAP5 protein levels with the translation modulation mechanism as the post-transcriptional axis." (PMID 36077054, 2022). "As a downstream target of YTHDF1-METTL14, E2F8 was first identified to be involved in DNA damage repair and chemoresistance in breast cancer." (PMID 35279688, 2022). "In this study, we found that ADAR1, an A-to-I RNA-editing enzyme, interacts with METTL3 mRNA and increases its protein level to promote the proliferation, migration and invasion of breast cancer cells through a mechanism connecting ADAR1, METTL3 and YTHDF1." (PMID 36077054, 2022). "The genetic depletion of YTHDF1 would significantly reduce the PKM2 abundance and inhibit glycolysis in breast cancer cells for effective tumor suppression." (PMID 35319018, 2022). "In breast cancer, eight genes (METTL3, KIAA1429, ZC3H13, FTO, YTHDF1, YTHDF2, IGF2BP2, and IGF2BP3) were significantly enriched in tumor cells compared to immune or stromal cells." (PMID 35794212, 2022). "Herein, we show that ADAR1, an A-to-I RNA-editing enzyme, interacts with METTL3 and increases its protein level to promote the proliferation, migration and invasion of breast cancer cells through a mechanism connecting ADAR1, METTL3 and YTHDF1." (PMID 36077054, 2022). "Inhibiting YTHDF1 would suppress the expression of the glycolytic gene PKM2 and impair the glycolytic activity of breast cancer cells, eventually leading to reduced proliferation and metastasis potential." (PMID 35319018, 2022). "Here, we found that YTHDF1 expression was distinctly related to T cells CD4 memory activated, macrophages M1, NK cells activated, and monocytes in breast cancer tissues." (PMID 34434939, 2021). "It has been reported that the m6A reader YTHDF3 promotes ribosome loading with YTHDF1, and a high YTHDF3 expression in breast cancer clinically correlates with brain metastases." (PMID 34976022, 2021). "These breast cancer patients with distinct molecular subtypes all represented lower expression of FTO, METTL3, and METTL14, and higher expression of YTHDF1 and YTHDF3 in tumor compared to the corresponding adjacent samples." (PMID 34804948, 2021). "Both YTHDF1 and YTHDF3 overexpression correlated with poor overall survival in breast cancer patients (all P values < 0.05)." (PMID 34044876, 2021). "Among them, the expression of RBM15, VIRMA, HNRNPA2B1, and YTHDF1/2/3 were significantly upregulated, but METTL3, METTL14, METTL16, WTAP, FTO, YTHDC1, and EIF3A had lower expression in breast cancer compared to normal samples." (PMID 34804948, 2021). "METTL3, METTL16, ZC3H13, YTHDC1 and FTO were expressed at a low level in breast cancer, while KIAA1429, RBM15, and YTHDF1 were expressed at a high level." (PMID 33362863, 2020). "By comparing tumor and normal samples, we found that six proteins were differentially expressed in breast cancer significantly (P < 0.001), including EIF3A, HNRNPA2B1, HNRNPC, RBMX, YTHDF1, YTHDF2." (PMID 33585234, 2020). "For Breast cancer 6 genes had significant aCGH/expression correlation at a level of 0.05 in all 7 breast cancer data sets (BCL9, AZIN1, TAF2, YTHDF1, TTC13, FBXL20)." (PMID 25148247, 2014). "Therefore, the overexpression of YTHDF1 in breast cancer cells largely augments the expression of FOXM1 and promotes breast cancer cell proliferation, invasion, and EMT." (PMID 40003882, 2025).
breast cancer (continued). "In triple-negative breast cancer, YTHDF1 is highly expressed in breast cancer tissue and cells, and knockdown of YTHDF1 significantly inhibits stemness and promotes the chemosensitivity of cancer cells." (PMID 39557826, 2024). "A ROC curve study was performed to explore the efficiency of YTHDF1 in distinguishing breast cancer samples (n = 1198) from normal samples (n = 113)." (PMID 38339157, 2024). "We created PPI networks to study the genes interacting with YTHDF1 in breast cancer (n = 1226) and their potential roles, and we carried out GO and KEGG correlation analyses using R and STRING to expand our understanding of the role of YTHDF1 in breast cancer." (PMID 38339157, 2024). "Furthermore, YTHDF1 expression exhibited notable correlations with activated CD4 memory T cells, M1 macrophages, activated NK cells, and monocytes in breast cancer tissues." (PMID 39199429, 2024). "Tumor hypoxia can induce HIF1, which post-transcriptionally inhibits the expression of miR-16-5p and promotes the expression of YTHDF1, which sequentially enhances tumor glycolysis via the up-regulation of PKM2, ultimately increasing the tumorigenic and metastatic potential of breast cancer cells." (PMID 38339157, 2024). "YTHDF1 targets FOXM1 mRNA and positively regulates breast cancer progression." (PMID 36999016, 2023). "This study found that YTHDF1 promotes EMT and breast cancer progression in breast cancer." (PMID 35075167, 2022). "YTHDF1 and YTHDF3 were also found to overexpress in breast cancer." (PMID 35721510, 2022). "Western blot analysis and cell cycle assay of the tumor cells from xenograft showed that YTHDF1 silence could inhibit EMT in vivo and induce G0/G1 phase cell cycle arrest of breast cancer cells." (PMID 35197112, 2022). "Furthermore, we have also comparatively analyzed the mRNA and protein levels of YTHDF1 in MCF 10A (a human normal breast epithelial cell line) and multiple breast cancer cell lines and observed similar trends (Original western blot data 2)." (PMID 35319018, 2022). "Additionally, other m6A regulators, YTHDF1 and ALKBH5, were also engaged in chemoresistance (including adriamycin, cisplatin, and olaparib) by enhancing DNA damage repair in breast cancer (BC)." (PMID 36517820, 2022). "In summary, our findings revealed the novel molecular pathway ADAR1/METTL3/ARHGAP5 connecting ADAR1, METTL3 and YTHDF1, which may indicate ADAR1 or METTL3 as prognostic and therapeutical targets for the treatment of breast cancer." (PMID 36077054, 2022). "Moreover, we demonstrated that YTHDF1 played a crucial role in promoting cell proliferation and invasion in cancer cells via the YTHDF1/FOXM1 axis, aggravating breast cancer progression and metastasis consequently." (PMID 35197112, 2022). "We validated the correlation between YTHDF1 and FOXM1 expression in breast cancer patients from TCGA by estimating the Pearson's correlation coefficient R. The result indicated a positive correlation (r = 0.31, P = 2.96e–29) between YTHDF1 and FOXM1 expression." (PMID 35197112, 2022). "In addition, YTHDF1, YTHDF2 and YTHDF3 are highly expressed in breast cancer and enhance cell proliferation, migration and invasion." (PMID 34044876, 2021). "Furthermore, the deceased patients had relatively reduced expression of FTO, METTL3, and METTL14 in tumor tissues, and increased levels of YTHDF1 and YTHDF3 than the alive patients who were diagnosed with breast cancer at the same period." (PMID 34804948, 2021). "High expressions of YTHDF1 and YTHDF3 were related to poor survival of patients with breast cancer." (PMID 34804948, 2021). "For example, the overexpression of YTHDF1 is related to poor prognosis in patients with liver cancer; downregulation of ALKBH5 in MDA-MB-231 human breast cancer cells can lead to a decrease in the number of breast cancer stem cells, resulting in a significant reduction in tumorigenic capacity." (PMID 32596399, 2020).
breast cancer (continued). "Additionally, CDH11 is frequently methylated in certain types of tumors, and it was reported that YTHDF1 translationally promoted CDH11 expression by recognizing m6A‐enriched sites of its transcript, thus promoting the osteolytic bone metastasis of breast cancer." (PMID 40387410, 2025). "The downstream targets of YTHDF1 may be related to MYC signaling regulation and T-cell differentiation, and YTHDF1 amplification resulted in reduced immune cell infiltration and significantly worse clinical features in breast cancer patients." (PMID 38339157, 2024). "In breast cancer, YTHDF1 and YTHDF3 are frequently amplified and consequently overexpressed, and significant correlations with intrinsic subclasses and nodal metastasis have been described, suggesting their use for prognosis stratification and therapeutic intervention in breast cancer." (PMID 37369946, 2023). "We show that both ADAR1 and METTL3 are upregulated in breast cancer samples, and ADAR1 positively correlates with METTL3; ADAR1 edits METTL3 mRNA and changes its binding site to miR532-5p, leading to increased METTL3 protein, which further targets ARHGAP5, recognized by YTHDF1." (PMID 36077054, 2022). "Since the expression of SIGLEC and YTHDF1 are higher in not basal-like breast cancer subtype, these genes might be more promising therapeutic targets for non-basal-like subtype or breast cancer patients with low CCR5 expression." (PMID 34717291, 2021). "SIGLEC15 and YTHDF1 are overexpressed in breast cancer and especially non-basal-like subtype." (PMID 34717291, 2021). "Moreover, YTHDF1 suppresses breast cancer apoptosis by m6A-mediated stabilization of aurora kinase A (AURKA) mRNA, while peptidyl-prolyl cis–trans isomerase NIMA-interacting 1 (PIN1) overexpression enhances YTHDF1 stability through inhibition of its degradation." (PMID 40986143, 2025). "In brief, we demonstrated that YTHDF1 binds to the m6A-modified FOXM1 gene at the coding sequence (CDS) region and plays its role as an oncogenic gene by promoting FOXM1 translation rather than transcription, exacerbating the progression of breast cancer." (PMID 35197112, 2022).